SAMHD1 (SAM and HD domain containing deoxynucleoside triphosphate triphosphohydrolase 1)
Diseases named in the same sentence as SAMHD1 in open-access papers (continued):
Sharing a sentence is not in itself a finding about the gene and the disease.
HIV-1 infection (continued). "The sterile alpha motif (SAM) domain- and histidine–aspartic acid (HD) domain-containing protein 1 (SAMHD1) potently restricts HIV-1 infection in non-cycling cells, such as macrophages, dendritic cells, and resting CD4+ T cells (1, –, 9)." (PMID 39162568, 2024). "In humans, sterile alpha motif (SAM) domain- and histidine–aspartic acid (HD) domain-containing protein 1 (SAMHD1) is a dNTPase enzyme that prevents HIV-1 infection in non-cycling cells, such as differentiated THP-1 cells and human primary macrophages." (PMID 39162568, 2024). "SAMHD1 is involved in various human diseases such as AGS neurodevelopmental genetic disorder, cancers, and HIV-1 infection in myeloid cells as well as multiple cellular events, such as cell cycle progress, dsDNA break repair, DNA replication fork processing, and anticancer activity of araC." (PMID 37567474, 2023). "As observed previously, WT SAMHD1 showed no restriction of HIV-1 infection in cycling U937 cells and neither did the Tetunstable group, T592S or T592E." (PMID 37127613, 2023). "Co-delivery of VLP-Vpx to SAMHD1 T592E KI mutant cells did not further enhance HIV-1 infection indicating the absence of additional SAMHD1-mediated anti-viral activity independent of T592 dephosphorylation." (PMID 37800914, 2023). "SAMHD1 dNTPase activity also restricts HIV-1 infection in other non-dividing cells, such as resting CD4 T cells and dendritic cells." (PMID 35893688, 2022). "To apply the KI approach to a functional analysis in the context of HIV-1 infection in resting CD4+ T cells, we introduced the eGFP gene upstream of the SAMHD1 locus to generate a GFP-SAMHD1 fusion protein, which is a Vpx-degradable and enzymatically active analog of non-tagged SAMHD1." (PMID 34949807, 2022). "As previously reported, expression of WT SAMHD1 rendered U937 cells resistant to HIV-1 infection, while the phosphomimetic T592E mutant failed to do so." (PMID 34321470, 2021). "SAMHD1 is most well-known for restricting HIV-1 infection in nondividing cells, where its dNTPase activity limits the dNTP levels below the threshold required for efficient HIV-1 late reverse transcription." (PMID 33177202, 2021). "An interesting finding of this study is that Vpx has the ability to trigger ISRE activation during HIV-1 infection to higher levels even in the absence of SAMHD1, indicating the involvement of a separate mechanism." (PMID 33563288, 2021). "SAMHD1 was described as restricting HIV-1 infection in DCs and myeloid cells by inhibiting reverse transcription due to limiting the deoxynucleoside triphosphate (dNTP) pool and thereby preventing HIV-1 infection of DCs and their activation." (PMID 34634939, 2021). "As SAMHD1 variants impaired for SUMO-conjugation to K469 and/or K622 efficiently blocked HIV-1 infection (RKR and QEN mutants), we deduced that SUMOylation of K595 might be crucial for viral restriction by SAMHD1." (PMID 34321470, 2021). "Addition of Vpx further enhanced HIV-1 infection in a virus input restricted environment, and viral spread was robust regardless of SAMHD1 consumption." (PMID 34440127, 2021). "Sterile-motif and HD-domain containing protein 1 (SAMHD1), a host restriction factor, is a deoxynucleoside triphosphate triphosphohydrolase (dNTPase), which interferes with HIV-1 infection in non-cycling immune cells." (PMID 34697376, 2021). "Despite significantly higher SAMHD1 levels in THP1 monocytes, HIV-C- and Vpx-mediated effects were also seen in WT THP1-DCs, which proves them to be a valuable model for studying functions of CR3 and CR4 in relation to HIV-1 infection in more detail." (PMID 32922405, 2020). "DCs however do not respond to HIV-1 infection owing to the block of reverse transcription resulting from SAMHD1 presence." (PMID 32181159, 2020). "Sterile alpha motif and HD-domain containing protein 1 (SAMHD1) was first described in 2011 as the restriction factor that gives non-dividing myeloid cells certain resistance against HIV-1 infection." (PMID 31708924, 2019).
HIV-1 infection (continued). "Surprisingly, however, both at the eclipse phase of infection as well as during late-stage chronic infection, HIV-1 infection suppressed baseline levels of IFI44 and showed similar trends with SAMHD1 and MX2 expression, indicating that HIV-1 actively shapes its environment." (PMID 30867315, 2019). "Importantly, upon entry into G1 phase, HIV-1 infection led to reduction of early and late RT products in activated CD4+ T and HeLa cells, depending on the presence of dephosphorylated SAMHD1." (PMID 29884836, 2018). "HIV-1 infection, however, did not alter SAMHD1 levels in macrophages as drastically, and the levels were more comparable to those seen in uninfected cells." (PMID 30656243, 2018). "Here, we demonstrate that HIV-1 efficiently infects macrophages without modulating SAMHD1 activity or cellular dNTP levels, and that macrophages permissive to HIV-1 infection remained refractory to superinfection by vpx-deleted SIV." (PMID 30656243, 2018). "NCS treatment, but not UV irradiation, induced a block to HIV-1 infection in the MDMs that resulted from the decrease of phosphorylated SAMHD1 levels." (PMID 29515139, 2018). "These experiments suggested that the inability of SAMHD1 C341S and C522S to block HIV-1 infection is not due to a change in the phosphorylation state of SAMHD1." (PMID 30044979, 2018). "We also provide an overview of the dynamic interplay between HIV-1, SAMHD1, and the cell-intrinsic antiviral response to elucidate how SAMHD1 modulates HIV-1 infection in non-dividing immune cells." (PMID 29176984, 2017). "SAMHD1 is widely expressed in diverse human tissues but in vitro appears to only restrict HIV-1 infection in non-dividing cells, perhaps because they typically have low nucleotide levels within the range of SAMHD1 control." (PMID 29056936, 2017). "However, during HIV-1 infection in vivo, activated CD4+ T-cells and macrophages are infected due to phosphorylation of SAMHD1." (PMID 29176984, 2017). "Therefore, the expression and distribution of SAMHD1 protein in subsets of HIV-1 target cells and its relationship with in vivo HIV replication in chronic HIV-1 infection need to be further investigated." (PMID 27922067, 2016). "Therefore, we performed qPCR and Western blot analysis to evaluate SAMHD1 expression in both control and anti-CCL2 Ab treated MDM at the time of HIV-1 infection (i.e., 20 h after treatment)." (PMID 25608886, 2015). "Together, these data indicate that the SAM domain has no influence on the timing or the magnitude of the SAMHD1-mediated block to HIV-1 infection." (PMID 26431200, 2015). "Since HIV-1 does not have a Vpx protein and HIV-1 Vpr is not capable of interacting with SAMHD1, myeloid cell types display resistance to HIV-1 infection." (PMID 24805990, 2014). "Importantly, we investigated the antiviral activity of cytoplasmic and nuclear SAMHD1 in MDM and confirmed that each form inhibited HIV-1 infection to a comparable degree." (PMID 24712655, 2014). "Neither Vpx addition nor SAMHD1 knock-down reversed the IFNα-induced blocks to HIV-1 infection seen in dividing U87-MG or THP-1 cells." (PMID 23442224, 2013). "However, the research on Vif has finally lead to the identification of APOBEC3G, which opens up a new era in the research field of host restriction factors in HIV-1 infection followed by TRIM5α, Tetherin/BST-2, and SAMHD1." (PMID 23430691, 2013). "SAMHD1 is thought to inhibit HIV-1 infection by depleting dNTP pools in nondividing cells to levels too low to be conducive for synthesis of proviral cDNA by viral reverse transcriptase." (PMID 23426366, 2013). "SAMHD1-mediated HIV-1 restriction in myeloid-lineage cells protects these cells from efficient HIV-1 infection, which likely prevents an innate immune response triggered by HIV-1 infection." (PMID 24523981, 2013). "Previously published reviews or commentaries have summarized the role of SAMHD1 in restricting HIV-1 infection in nondividing human immune cells." (PMID 24523981, 2013).
HIV-1 infection (continued). "Taken together, our data reveal that SAMHD1, while previously established as an important regulator of HIV-1 infection, is not a major effector of IFNα-mediated HIV-1 restriction in a number of cell types and lines." (PMID 23442224, 2013). "Phosphorylation of SAMHD1 regulates the capability of SAMHD1 to block HIV-1 infection but not the ability to decrease the cellular levels of dNTPs." (PMID 24219908, 2013). "In agreement with Goldstone and colleagues, we have established that SAMHD1 is an oligomeric protein in mammalian cells; however, the contribution of oligomerization to the ability of SAMHD1 to block HIV-1 infection is not understood." (PMID 24219908, 2013). "SAMHD1 is expressed at constitutively high levels by cells which are nonpermissive with regards to HIV-1 infection, such as monocytes and monocyte-derived DC." (PMID 24455433, 2013). "Broader understanding of the mechanism of SAMHD1-mediated restriction in non-dividing cells and further investigation of the biological role of SAMHD1 is vital to enhancing our knowledge of HIV-1 infection and pathogenesis." (PMID 23231760, 2012). "In addition, localization studies of the Vpx protein during SIV or HIV-1 infection correlated the nuclear localization of Vpx with its ability to promote productive infection in primary macrophages, suggesting that Vpx might overcome the viral-block imposed by SAMHD1 in the nucleus." (PMID 22691373, 2012). "Further studies are needed to delineate the cellular mechanism by which SAMHD1 inhibits HIV-1 infection in non-cycling cells." (PMID 23092163, 2012). "In summary, these live cell microscopy experiments support the notion that within non-stimulated PBMC lacking functional SAMHD1, CD14+ monocytic cells are the subpopulation that are highly susceptible to HIV-1 infection." (PMID 22174685, 2011). "SAMHD1 knockdown in THP-1 cells results in more than 10-fold increase in HIV-1 replication; in contrast to the enormous effect of Vpx in IFN-treated MDDCs, HIV-1 infection of IFN-treated THP-1 cells increases only two to three-fold in response to Vpx." (PMID 21696578, 2011). "We provide new insights into the ability of SAMHD1 to protect monocytic cells from HIV-1 infection by using primary cells from patients with Aicardi-Goutières syndrome (AGS) lacking endogenous SAMHD1 expression." (PMID 22174685, 2011). "It is not clear whether the newly synthesized or cytosolic SAMHD1 that participates in MxB cytoplasmic traps against viral capsid can undergo K595 SUMOylation upon HIV-1 infection." (PMID 40277359, 2025). "SAMHD1 was undetectable in U937 EV cells both in the presence and absence of HIV-1 infection." (PMID 40434097, 2025). "SAMHD1 did not inhibit HIV-1 infection at 2 and 3 dpi in dividing THP-1 cells." (PMID 40434097, 2025). "Interestingly, BIK expression was increased by HIV-1 infection at 8 dpi only in THP-1 Ctrl cells but not in SAMHD1 KO cells based on the average of three independent experiments." (PMID 40434097, 2025). "However, several early reports challenged the correlation and showed that pSAMHD1T592 does not necessarily inhibit dNTPase activity but renders SAMHD1 non-restrictive to HIV-1 infection." (PMID 40277359, 2025). "However, the effects of different SAMHD1 acetylation states on its ability to restrict HIV-1 infection have not yet been studied." (PMID 39162568, 2024). "Thus, increased MX2 expression after IFNα treatment had a limited effect on HIV-1 infection in the U937 cells lacking SAMHD1, but in the SAMHD1-expressing U937 cells, IFNα treatment both increased MX2 expression and promoted HIV-1 suppression." (PMID 38888311, 2024). "Of note, both THP-1 Ctrl and SAMHD1 KO cells lacking IRF7 expression showed lower levels of HIV-1 infection, suggesting that IRF7 may promote HIV-1 infection in THP-1 cells." (PMID 37328105, 2023).
HIV-1 infection (continued). "Interestingly, HIV-1 infection was not further enhanced by SAMHD1 T592E mutant depletion suggesting the absence of an additional anti-viral activity of SAMHD1 that is independent of T592 dephosphorylation." (PMID 37800914, 2023). "TAK1 inhibition attenuates HIV-1 infection in THP-1 cells lacking SAMHD1 expression." (PMID 33177202, 2021). "Sterile alpha motif and HD domain-containing protein 1 (SAMHD1) is a deoxynucleoside triphosphate triphosphohydrolase (dNTPase) that restricts human immunodeficiency virus type 1 (HIV-1) infection in nondividing cells of myeloid lineage and resting CD4-positive (CD4+) T cells." (PMID 33177202, 2021). "This drug successfully prevented IRF3 translocation to the nucleus, but could not prevent G1-to-G0 transitioning, SAMHD1 dephosphorylation, and blockade of HIV-1 infection." (PMID 32209460, 2020). "HIV-1 infection is also restricted by SAMHD1 in resting CD4+ T cells but not in activated T cells." (PMID 31426525, 2019). "While DNA damage agents are not likely to be useful in the treatment of HIV-1 infection, it may be possible to control the SAMHD1 phosphorylation state by targeting intracellular signal transduction in MDMs, thereby reducing virus loads." (PMID 29515139, 2018). "Our data highly suggested that p21 could suppress the expression of RNR2 and block the phosphorylate SAMHD1 simultaneously in non-cycling cells so as to restrict HIV-1 infection through regulating cellular dNTPs." (PMID 29587790, 2018). "The experiments in in vitro cell cultures demonstrate that SAMHD1 restricts HIV-1 infection in non-dividing cells such as macrophages (plus phorbol 12-myristate 13-acetate-stimulated macrophage-like THP-1 cell line), DCs, and resting CD4+ T cells by degrading dNTPs." (PMID 29379496, 2017). "Moreover, the phosphorylation of SAMHD1 at T592 negatively regulates its RNase activity in cells and impedes HIV-1 restriction, suggesting that the RNase activity of SAMHD1 is responsible for preventing HIV-1 infection by directly degrading viral RNA." (PMID 29379496, 2017). "However, SAMHD1 shows comparable expression in monocytes compared with MDDCs, suggesting that VprBP-facilitated HIV-1 infection in MDDCs is not attributed to the SAMHD1 degradation induced by CUL4–DDB1–DCAF1/VprBP E3 ubiquitin protein ligase complex." (PMID 24932481, 2014). "Western blot analysis showed that Vpx-VLPs induced the degradation of SAMHD1 under all conditions, indicating that IFNα-mediated suppression of HIV-1 infection in dividing and non-dividing THP-1 cells is maintained to significant degrees following SAMHD1 removal." (PMID 23442224, 2013). "SAMHD1 expression also did not inhibit HIV-1 infection in HEK293T cells." (PMID 24035396, 2013). "In contrast to the dimeric model suggested from the structural work, functional analyses of catalytic and anti-HIV activities of SAMHD1 have demonstrated that tetramerization of SAMHD1 is critical for its dNTPase activity and restriction of HIV-1 infection in nondividing cells." (PMID 24523981, 2013). "Similarly, Vpx from HIV-2 or SIVsm degrades SAMHD1 in resting CD4+ T-cells and efficiently increases single-cycle and replication-competent HIV-1 infection, which is correlated with increased products of full-length viral cDNA and 2-LTR circles in infected cells." (PMID 23092163, 2012). "Post-transcriptional regulation and/or post-translational modifications of SAMHD1 might be important for its function in restricting HIV-1 infection in non-cycling cells." (PMID 23092163, 2012). "However, in contrast to SAMHD1, TREX1 and RNAseH2A have been shown to facilitate HIV-1 infection." (PMID 23336082, 2012). "However, several known SAMHD1 mutations decrease cellular dNTP levels without restricting HIV-1 infection, suggesting that the dNTPase activity of SAMHD1 is necessary but not sufficient to enable the blockade of HIV-1 infection by SAMHD1 (13, –, 18)." (PMID 39162568, 2024).
HIV-1 infection (continued). "However, THP-1 cells are not restrictive to HIV-1 infection, and it is still unclear whether SAMHD1-mediated HIV-1 restriction can be solely attributed to its dNTPase function." (PMID 33177202, 2021). "In addition, SAMHD1 dNTPase activity restricts HIV-1 infection in nondividing myeloid cells." (PMID 34492268, 2021). "Therefore, although it has been previously shown that SAMHD1 affects HIV-1 infection, we argue that SAMHD1 elimination is not necessary for HIV-1 (or RT-HSIV) to reverse transcribe in macrophages; Vpx and SAMHD1 knockdown only serve to boost HIV-1 infectivity but are not necessary for it." (PMID 30656243, 2018). "Interestingly, we observed higher early and late HIV-1 RT products upon HIV-1 infection in absence of Vpx (-Vpx) in mitotic cells, which displayed high SAMHD1 pT592-levels (“inf + N”), than compared to CD4+ T cells that entered G1 phase characterized by a reduced pT592 signal (“inf”) (“-Vpx”)." (PMID 29884836, 2018). "Moreover, HIV infection is made possible despite the lack of a viral factor counteracting SAMHD1 by different cellular proteins: CD81 for example has recently been shown to favor HIV-1 infection by interacting with SAMHD1 and stimulation of its proteasome-dependent degradation." (PMID 29088112, 2017). "The dNTPase activity of SAMHD1 has been intensively investigated in the context of retroviral restriction; however, it is not known whether the newly identified RNase activity of SAMHD1 has a unique ability to control HIV-1 infection or whether it can also control infection by other viruses." (PMID 26032178, 2015). "Our studies in U87-MG and THP-1 cells, where manipulation of SAMHD1 fails to overcome the effects of IFNα, allude to the existence of additional, possibly cell type specific, IFNα-inducible (and Vpx-independent) inhibitors of the early stages of HIV-1 infection." (PMID 23442224, 2013). "HIV-1 infection of SAMHD1-expressing THP-1 cells did not further promote BIK protein expression by 4 dpi, at which SAMHD1-enhanced apoptosis was already observed." (PMID 40434097, 2025). "Loss of BIK expression reverted Δψm in SAMHD1-expressing THP-1 cells, but not in SAMHD1 KO cells, upon HIV-1 infection, suggesting that BIK is required for SAMHD1-enhanced mitochondrial depolarization by HIV-1." (PMID 40434097, 2025). "Taken together, these results demonstrate that addition of Vpx during HIV-1 infection increases type I IFN and ISRE induction even in the absence of SAMHD1." (PMID 33563288, 2021). "SAMHD1 activity is not correlated with its expression levels, as only resting CD4 T cells restrict HIV-1 infection." (PMID 24167505, 2013). "However, HEK293T cells, undifferentiated THP-1 cells and activated CD4+ T cells are not refractory to HIV-1 infection despite expressing SAMHD1, suggesting that the antiviral activity of SAMHD1 may be biologically important only in differentiated or non-dividing cells such as DC and macrophages." (PMID 24455433, 2013). "HIV-1 infection does not typically induce potent innate immune responses; however, we have reported significant induction of the NF-κB pathway in THP-1 cells lacking SAMHD1 expression." (PMID 33177202, 2021). "In addition, a monocytic cell line called THP-1 becomes resistant to HIV-1 infection after differentiation into macrophages with PMA treatment, even though PMA treatment does not change the expression of SAMHD1." (PMID 26134849, 2015). "SAMHD1 is expressed at similar levels in MDMs, resting CD4+ T cells and in activated CD4+ T cells, but does not block HIV-1 infection in the latter." (PMID 24782834, 2014). "Further elucidating the mechanisms of SAMHD1-mediated HIV-1 restriction in non-cycling myeloid cells and resting CD4+ T-cells may help develop new therapeutic approaches against HIV-1 infection." (PMID 23092163, 2012).